SSX1 (SSX family member 1)
Diseases named in the same sentence as SSX1 in open-access papers (continued):
Sharing a sentence is not in itself a finding about the gene and the disease.
epithelial ovarian cancer (1 paper, 2023). "In our early work, we performed microarray profiling to identify putative targets of KIAA1456 that might be involved in ovarian cancer suppression and found that SSX1 is the most strongly downregulated gene in KIAA1456-overexpressing cells." (PMID 37056382, 2023). "Little is known whether SSX1 is involved in KIAA1456's regulation of proliferation and apoptosis in epithelial ovarian cancer cells." (PMID 37056382, 2023).
hepatocellular carcinoma (1 paper, 2023). A malignant tumor that arises from hepatocytes. "High SSX1 and SSX2 expression levels were observed in patients with hepatocellular carcinoma, which suggests that they might be used as a cancer marker." (PMID 37241221, 2023).
leukemia (1 paper, 2023). A malignant (clonal) hematologic disorder, involving hematopoietic stem cells and characterized by the presence of primitive or atypical myeloid or lymphoid cells in the bone marrow and the blood. "This screening was conducted to determine the specificity of SSX1, SSX2, and SSX3 in additional cancer tissue samples, including leukemia in males and BC in females." (PMID 37241221, 2023).
ovarian tumor (1 paper, 2019). "In addition, aberrant expression of SSX-1, SSX-2, or SSX-4 was identified in 26% of ovarian tumor specimens, and SSX-1, SSX-2, and SSX-4 expression was detected in 2.5%, 10%, and 16% of 120 EOC specimens, respectively." (PMID 30609934, 2019).
prostate carcinoma (1 paper, 2023). A carcinoma that arises from epithelial cells of the prostate gland. "In prostate cancer, for example, it has been observed that SSX1 expression is restricted to metastatic lesions in prostate cancer, with increased SSX1 expression observed in patients with advanced disease compared to healthy donors and patients with early-stage disease." (PMID 36649303, 2023).
tumor (51 papers, 2001 to 2025). "One network comprises well known cancer antigens (e.g. GAGE1, MAGEB2, MAGEC2 and SSX1) associated with short overall survival and additional aggressive tumour properties." (PMID 36649303, 2023). "None of the blood samples with known synaptotagmin (SYT; SS18)::SSX family member 1/2 (SSX1/2) fusions in the primary tumour had detectable cfRNA." (PMID 39797974, 2025). "The data demonstrates that TAK-981 efficiently inhibits tumor growth in SS18::SSX1 fusion containing ASKA-SS as well as SYO1 cell lines." (PMID 40804185, 2025). "The main function of SSX1 is to form fusion genes with multiple genes, thereby demonstrating its impact on the biological function of tumor cells." (PMID 37483501, 2023). "Synovial sarcoma X chromosome family member 1 (SSX1) promotes tumor cell metastasis and leads to tumor deterioration." (PMID 34177903, 2021). "The SYT gene (Chr 18) fuses with SSX1 (Chr X) to form biphasic tumour while fusion with SSX2 leads to monophasic tumour." (PMID 27446625, 2016). "The additional nucleotides corresponded to 136 bp of complete exon 6 of RALBP1 associated Eps domain containing 2 (REPS2) (NM_004726.2) and 50 bp of complete exon 5 of SSX1, indicating a complex rearrangement in this tumor." (PMID 22976541, 2012). "Further molecular studies are needed to elucidate the different implications and/or interactions of SYT::SSX1/2/4 and the role of BCL-2 in SS tumor onset and growth." (PMID 40416104, 2025). "As each SS tumor harbors a unique breakpoint sequence within SYT and one of three SSX genes (SSX1, SSX2 and SSX4) forming the tumor-specific translocation t(x;18)(p11.2;q11.2), these breakpoint sequences can be used for ctDNA detection." (PMID 35565213, 2022). "Intriguingly, these tumor-specific gene fusion events contain one TF of SSX2 and seven oncogenes of SS18, SSX1, SSX2, BCOR, CNOT1, HIST2H2AC, and TOP1." (PMID 36118864, 2022). "At least nine different SSX gene transcripts, SSX1 to SSX9, have been identified, and the SSX gene transcript type is related to the histologic subtype and biological nature of the tumor." (PMID 32691176, 2020). "While Xq chromothripsis was present in this tumor, no apparent copy‐number changes were found at Xp where SSX1 is located." (PMID 40159593, 2025). "Finally, IHC with SS18-SSX fusion-specific antibody gave diffuse positive staining to the tumor cells, and fusion gene analysis using mRNA extracted from paraffin sections revealed that the tumor had SS18 (SYT)-SSX1 fusion gene." (PMID 34895269, 2021). "In this analysis they found that SSX1, 2, and 4 were expressed in 8%, 15%, and 15% of tumors, respectively, with no detection of SSX3 in any samples and detection of SSX5 in only 7 out of the total 325 tumor specimens evaluated." (PMID 20981248, 2010). "As before, no endogenous processing and presentation of SSX1 epitopes by tumor cells was demonstrated." (PMID 20981248, 2010). "There were 10 lncRNAs that were expressed in more than 20% of the tumor samples (LINC01980, AC025254.1, LINC02806, LINC02476, LINC02506, AL162413.1, LINC00221, LINC01287, AC079466.1, and LINC01419), compared to five protein-coding genes (MAGEA1, MAGEA3, SSX1, DCAF4L2, and MAGEC2)." (PMID 38985879, 2024). "However, in contrast to SSX1/2, RT-PCR data from 44 SS tumor samples revealed that SSX3 was not a fusion partner with SS18." (PMID 20981248, 2010). "In the case of both genes, it was observed that the last 78 C-terminal amino acids of SSX1 and SSX2 replaced the last 8 amino acids of the C-terminus of SS18 in most tumors, however, alternate fusions were also observed less frequently for some tumor specimens." (PMID 20981248, 2010). "For instance, a SS case that was previously shown to be negative for SYT/SSX1 and SYT/SSX2 gene expression by conventional RT-PCR, was instead found to be SYT/SSX4 positive, as the sole fusion transcript expressed in this tumor sample, when the RT-PCR was redesigned." (PMID 29751751, 2018).
cancer (17 papers, 2010 to 2025). A tumor composed of atypical neoplastic, often pleomorphic cells that invade other tissues. "In respects, SSX1 is an excellent candidate target of cancer immunotherapy, as it is frequently expressed in cancer cells." (PMID 37056382, 2023). "According to these findings, in Intestinal GC, the chrXq28 band resulted in significantly associated activity between SSX1, SSX4 and SOLHLH1 MRs, which are involved in stem cell maintenance and are indicated as cancer and testis antigens." (PMID 36230884, 2022). "Other genes overexpressed in Cluster 1 were chemokine and cytokine related genes (CCL15, CCL18, TNF, IL11RA, XCR1), the immune checkpoint protein PD-1 (PDCD1), and cancer-related genes (SSX1 and MAGEA4)." (PMID 33298930, 2020). "Under the differentially expressed genes we identified several genes previously related to cancer including the up-regulated SSX1, SSX2, RXFP2, RYR2 and the down-regulated CSTA, TSPAN7, NEO1, S100A, SERPINB5 and SEPP1." (PMID 25857299, 2015). "In this study an overlapping pool of peptides spanning the entire SSX1 protein sequence was incubated with PBMCs from cancer-free individuals; SSX1-peptide-specific CD4+ T cells were identified in 5/5 of the donors analyzed." (PMID 20981248, 2010). "This could suggest that they play a key role in maintaining mesenchymal cell stemness, and that increased SSX1 expression could reflect a cancer stem cell phenotype." (PMID 20576167, 2010). "Two protein-protein interaction networks were observed for genes upregulated in solid cancer: one network included products of cancer-specific genes such as MAGEB2, MAGEC2 and SSX1 for the whole cohort." (PMID 36649303, 2023). "This confirms previous research results, demonstrating increased SSX1 and SSX2 expression levels in numerous cancers, including CC." (PMID 37241221, 2023). "Agilent design did not include one or more exons containing at least one cancer-linked mutation listed in COSMIC for 4 out of 112 genes (BRCA1, KMT2C, H3F3A, and SSX1) (data not shown)." (PMID 27578032, 2016). "Although the function of these proteins remains unknown, SSX1/SSX2 overexpression has been known to regulate stem cell migration, suggesting significant role in metastasis in cancer tissue." (PMID 25401222, 2014). "Another contributing factor could be the fact that a number of cancer-related genes, known as cancer/testis antigens (CTAs) that are located on the X-chromosome (MAGEA1, SSX1, SSX4, and CTAG1/2), are highly upregulated in PBL, which mainly affect male individuals." (PMID 26108914, 2015).
blood cancers (1 paper, 2023). "Notably, upregulated genes in short survival cases across solid and blood cancer cohorts include a common immune gene signature comprising MAGEC2, SSX1 and ULBP2." (PMID 36649303, 2023). "Three upregulated genes were common to both solid and blood cancers (MAGEC2, SSX1, ULBP2), but there were no common downregulated genes." (PMID 36649303, 2023).
SSX1 also shares sentences with these, for which no sentence is quoted: Ewing sarcoma (5 papers); chronic myelogenous leukemia (4); alveolar rhabdomyosarcoma (3); soft tissue tumor (3); myxoid liposarcoma (2); soft tissue sarcoma (2); acute myeloid leukemia (1); adenocarcinoma (1); brain tumour (1); clear cell sarcoma (1); Cushing syndrome (1); desmoplastic small round cell tumor (1); epithelioid hemangioendothelioma (1); female infertility (1); gastric cancer (1); glioma (1); head and neck cancer (1); hemangiopericytoma (1); Hodgkins lymphoma (1); infection (1); lung carcinoma (1); oligoastrocytoma (1); ovarian cancer (1); pleomorphic liposarcoma (1); spindle cell sarcoma (1); spindle cell tumor (1); undifferentiated pleomorphic sarcoma (1).